GTF2I (general transcription factor IIi)
Diseases named in the same sentence as GTF2I in open-access papers (continued):
Sharing a sentence is not in itself a finding about the gene and the disease.
thymoma (continued). "In sum, the phenotype of mouse TECs expressing the mutant Gtf2i gene is best characterized as an A type-like thymoma, although some features of human AB-type and B-type thymomas are also present." (PMID 36175547, 2022). "GTF2I mutation is the most common molecular alteration in TET, specifically in type A and AB thymomas where it occurs in 70 to 100% of cases." (PMID 35198446, 2022). "Previous analyses have demonstrated recurrent missense GTF2I mutations in WHO histologic type A and AB thymomas." (PMID 34136086, 2021). "We demonstrated a widespread distribution of mutant GTF2I in all types of thymomas, including type B. The SIFT and Polyphen 2 algorithms predicted that the GTF2I mutation (p.L424H) was somatic and altered protein structure and function." (PMID 32722121, 2020). "Mutant GTF2I was detected in at least one sample from all the subtypes of thymomas (A, AB, B1, B2, and B3)." (PMID 32722121, 2020). "Thus, the GTF2I mutation may well be called a prevalent mutation in thymomas in general." (PMID 32722121, 2020). "Gene mutations previously reported in type A and AB thymoma (e.g., GTF2I, HRAS, KRAS) were not identified in our cohort." (PMID 41344988, 2026). "Type A/AB thymomas carry no or few chromosomal alterations but a recurrent GTF2I mutation as the basic driver." (PMID 38473304, 2024). "GTF2I mutations have an allele frequency ranging from 4% to 22% due to the dilution of non-tumoral thymocytes and stromal cells within thymoma samples." (PMID 37671056, 2023). "Even if GTF2I mutations are common in A and AB thymomas, there are no clinically relevant targets in TETs except for KIT mutations observed in only 10% of thymic carcinomas." (PMID 37671056, 2023). "Furthermore, our investigation unveiled an elevated abundance of cTECs and TEPCs within the thymic tissues isolated from mouse thymic tissue, thereby suggesting a potential cellular origin of GTF2I-mutant thymomas from these distinct cell populations." (PMID 37849766, 2023). "Due to the limited studies exploring the relationship between GTF2I mutations and TIME worldwide, we investigated the differences in the TIME between TET patients with GTF2I mutant thymoma and wild-type, with the aim to illustrate prognostic differences between the two groups." (PMID 36114454, 2022). "Finally, the highly characteristic L424H mutation of the GTF2I gene is encountered in both MNT and A-thymomas." (PMID 36497358, 2022). "For example, GTF2I is specific to thymomas, whereas GNAQ and GNA11 are specific to uveal melanomas." (PMID 35975235, 2022). "Although the spindle cell component of this biphasic thymoma type vaguely resembles spindle cell areas in type A and AB thymomas, GTF2I mutations were consistently absent." (PMID 33674910, 2021). "While Alphaproteobacteria were detected in a significantly high number of cases without the driver mutation in the GTF2I gene, a clear pathway involved in the oncological development of thymoma without a driver mutation remains to be demonstrated." (PMID 34834444, 2021). "The GTF2I L424H mutation was a newly identified recurrent genomic variation in A and AB subtypes of thymomas Since the gene was not covered by our gene panel, we analyzed the RNA-seq data for the mutation status of GTF2I in our cohort." (PMID 34568003, 2021). "Alphaproteobacteria was dominant in thymomas without the GTF2I mutation, while Gammaproteobacteria was dominant in thymomas harboring the GTF2I mutation." (PMID 34834444, 2021).
thymoma (continued). "In addition, the PLR was significantly higher in thymomas with mutant GTF2I than those with wildtype GTF2I (thymomas with mutant GTF2I, 137.2 ± 13.1; thymomas with wildtype GTF2I, 97.0 ± 15.7; p < 0.05)." (PMID 32722121, 2020). "However, the majority (82% to 100%) of type A thymomas harbor a GTF2I mutation which is absent in metaplastic thymomas." (PMID 38067300, 2023). "For example, the absence of a mutant General Transcription Factor II‐I (GTF2I) oncogene verifies the diagnosis of thymic cancer since these oncogenes are only seen in thymomas." (PMID 40249565, 2025). "A trend for the absence of co-occurrence with GTF2I was observed also for CDKN2A, BAP1, CYLD, and KIT mutations, which are genes frequently mutated in B3 thymomas and thymic carcinomas." (PMID 37671056, 2023). "The presence of mutant GTF2I in type B thymomas, in addition to type A thymomas, in this study, unlike previous studies, can be attributed to three reasons." (PMID 32722121, 2020). "Indeed, GTF2I is a thymoma-specific oncogene, unique to TETs and not found in other human cancers." (PMID 36836670, 2023).
Williams-Beuren syndrome (24 papers, 2006 to 2025). "For example, in Williams Syndrome, phobias related to auditory stimuli are commonly reported and have been associated with hyperacusis, and the deletion of GTF2I is associated with low rates of social anxiety." (PMID 35304663, 2023). "Most notably, GTF2I haploinsufficiency is associated with Williams-Beuren Syndrome (WBS) a neurodevelopmental disorder with specific craniofacial features." (PMID 36756127, 2023). "The GTF2I gene is well known for its association with Williams-Beuren syndrome and supravalvular aortic stenosis." (PMID 34113352, 2021). "The general transcription factor 2I, GTF2I (protein TFII-I), is one of ~ 25 genes encoded within the chromosome 7q11.23 region commonly deleted or duplicated in Williams syndrome (WS) (MIM:194050) and Dup7q11.23 (MIM:609757), respectively." (PMID 30120731, 2019). "Third, studies of segregating genetic variation for genes within the Williams-syndrome deletion region have identified an association of several SNPs in GTF2I with autism." (PMID 25429715, 2014). "Several lines of evidence have linked the gene GTF2I (General Transcription Factor IIi) with the social phenotypes of Williams syndrome, but a role for this gene in sociality within healthy populations has yet to be investigated." (PMID 25429715, 2014). "Taken together, these lines of evidence regarding the causes of the Williams syndrome region cognitive-behavioral phenotypes suggest important roles for the GTF2I gene." (PMID 25429715, 2014). "Williams syndrome (WS) is a multisystem neurodevelopmental disorder caused by a de novo hemizygous deletion of ~26 genes from chromosome 7q11.23, among them the general transcription factor II-I (GTF2I)." (PMID 35011720, 2022). "Human genetic association studies and investigations of Gtf2i-deficient mice suggest that GTF2I may be a major contributor to the hypersocial phenotype seen in William’s syndrome patients." (PMID 27014003, 2016). "The phenotype of Srcthl/thl mice showed significant overlap with Williams-Beuren syndrome (WBS), a disorder caused by the deletion of several genes, including General Transcription Factor 2-I (GTF2I)." (PMID 26464974, 2015). "This included data from Gtf2i-knockout mouse brain, brain biopsies from Williams-Beuren Syndrome (WS) patients with a microdeletion including GTF2I, WS iPSC and WS fibroblasts." (PMID 39136782, 2024). "Similar mitochondrial issues were demonstrated by Gtf2i heterozygous model, mirroring the human condition in Williams syndrome (WS), and by hemizygous neuronal Gtf2i deletion model, indicating Gtf2i’s dosage-sensitive role in mitochondrial regulation." (PMID 38097729, 2023). "A neurobiological study reveals Gtf2i’s pivotal roles in brain development and mediating neuronal mitochondrial function, validated by human brain samples derived from individuals with Williams syndrome." (PMID 38097729, 2023). "Previous works showed GTF2I involved in Williams-Beuren syndrome, but pathways affected by GTF2I are indistinct." (PMID 33859276, 2021). "GTF2I has been reported to be one of the major genes responsible for neurological deficits in Williams-Beuren syndrome." (PMID 28552951, 2017). "Experimentally generated mutant mice heterozygotic for Gtf2i and for its related transcription factor Gtf21-rd1 featured anomalies similar to those observed in Williams-Beuren Syndrome: retarded growth, microcephaly and craniofacial and skeletal defects." (PMID 20642858, 2010). "The GTF2I gene is commonly deleted in Williams-Beuren syndrome (WBS), a neurodevelopmental disorder characterized by craniofacial dysmorphology, intellectual disability, deficits in visuospatial construction, relative strength in concrete language, social disinhibition, and nonsocial anxiety." (PMID 26464974, 2015).
Williams-Beuren syndrome (continued). "GTF2I codes for the transcription factor TFII-I that is highly expressed in the brain, and it belongs to a small paralogous gene family of transcriptional regulators that includes two other genes in the Williams-syndrome region, GTF2IRD1 and GTF2IRD2 that interact with one another in their effects." (PMID 25429715, 2014). "GTF2I and the functionally related GTF2IRD1 are two of up to 28 genes deleted in the microdeletion syndrome Williams-Beuren Syndrome (WS; OMIM #194,050)." (PMID 39136782, 2024). "GTF2I codes for a general intrinsic transcription factor and calcium channel regulator TFII-I, with high and ubiquitous expression, and a strong candidate for involvement in the morphological and neuro-developmental anomalies of the Williams-Beuren syndrome (WBS)." (PMID 20403157, 2010).
Anxiety (9 papers, 2010 to 2025). Intense feelings of nervousness, tension, or panic often arise in response to interpersonal stresses. "In particular, the neuronal deletion of the General transcription factor II-I gene (Gtf2i) has been shown to cause myelination deficits, which have been linked to behavioural atypicalities such as motor deficits, increased sociability, and anxiety, in mice." (PMID 34743752, 2021). "Recent analysis of a Gtf2i heterozygous deficient mouse also identified increased measures of social interaction, but no deficits in growth, craniofacial morphology, motor performance, startle response, or anxiety." (PMID 26464974, 2015). "Second, mouse single-gene knockouts have indicated that GTF2I gene dosages modulate levels of sociality, with hemizygosity leading to higher levels of less-discriminate social interaction, and triploidy, which corresponds to the duplication, being associated with higher social anxiety." (PMID 25429715, 2014). "Behavioral assessment of Gtf2i-KO mice revealed enhanced motor coordination, increased anxiety-like behavior, and heightened sociability compared to controls." (PMID 41006289, 2025). "The results showed a trend towards higher anxiety levels in Gtf2i-KO mice, indicated by their spending less time in the open arms compared to controls (mean control 249.1 ± 19.62 s, mean Gtf2i-KO 200.3 ± 16.59 s)." (PMID 41006289, 2025). "Gtf2i-KO mice exhibited a higher level of anxiety-like behavior, spending significantly more time in the margins of the arena than did controls." (PMID 41006289, 2025). "Together, these data suggest that Gtf2i-KO mice possess improved motor coordination, moderately increased anxiety-like behavior, and demonstrate increased sociability, as compared to controls." (PMID 41006289, 2025). "The selective deletion of Gtf2i from excitatory neurons of the forebrain resulted in WS-relevant abnormalities, including neuroanatomical defects and increased sociability and anxiety." (PMID 35011720, 2022). "Variable-sized deletions have also been generated in mouse models, which have implicated the region including GTF2I, GTF2IRD1, LIMK1, and intervening genes, in sociality and anxiety phenotypes." (PMID 25429715, 2014). "In summary, a significant phenotype was obvious in Gtf2i+/Δex2 animals with decreased exploratory activity, higher anxiety and a lower threshold for sound intolerance." (PMID 20403157, 2010). "AAV-based post-natal Gtf2i gene therapy in a mouse model of WS in which there is complete pre-natal deletion of the WSCR resulted in the restoration of mouse (m)Gtf2i levels, alongside improved motor coordination and sociability, as well as decreased anxiety, as compared to controls." (PMID 37626769, 2023). "Increased levels of anxiety were remarked in Gtf2i+/Δex2 mice in the different paradigms used." (PMID 20403157, 2010). "Furthermore, the observed hypermyelination in the SN of Gtf2i-KO mice raises the possibility that PNS myelination changes contribute to motor coordination improvements, while CNS myelination abnormalities may play a role in altered anxiety and sociability behaviors." (PMID 41006289, 2025). "Overall, the results from the various assays do not support the hypothesis of a hyposocial phenotype in Gtf2i+/dup mice, although this does not eliminate the potential for other ASD‐like traits in these mice such as heightened separation anxiety as has been previously reported." (PMID 29568691, 2018).
thymic carcinoma (8 papers, 2021 to 2023). Thymic carcinoma (TC) is a type of thymic epithelial neoplasm characterized by a high malignant potential. "In this way, the mutation could be induced at different time points during the lifetime of the mouse to explore whether Gtf2i mutations occurring early in life may remain dormant until adulthood, or whether they are more likely to lead to thymic carcinomas." (PMID 36175547, 2022). "Thymomas, but not thymic carcinomas, often harbor GTF2I mutations." (PMID 38201593, 2023).
autism spectrum disorder (6 papers, 2015 to 2023). A spectrum of developmental disorders that includes autism, and Asperger syndrome. "While widely studied in the context of the hypersociability and the neurocognitive aspects in WS23,30–32,35,42,106, Gtf2i mutations and altered expression are also related to autism spectrum disorders caused by duplication of 7q11.23107–111 and cancer." (PMID 38097729, 2023). "GTF2I gene dosage is further ascribed to autism spectrum disorder (ASD) and single nucleotide polymorphisms in GTF2I loci are associated with autoimmune disorders like SLE, RA and Sjogren syndrome, and reviewed in." (PMID 36756127, 2023).
autoimmune disease (6 papers, 2021 to 2025). A disorder resulting from loss of function or tissue destruction of an organ or multiple organs, arising from humoral or cellular immune responses of the individual to their own tissue constituents. "In this study, we proposed the splicing of GTF2I played a role in B cell proliferation, which expanded the scope of AS-regulated immune response and potentially implicated in other autoimmune diseases such as RA and SLE." (PMID 40007754, 2025). "Therefore, GTF2I wild-type TET patients were more likely to form autoimmune diseases as well as develop symptoms of MG than patients with a mutant type." (PMID 36114454, 2022).
breast carcinoma (6 papers, 2011 to 2024). "It is reported that GTF2I was found to have potential prognostic value for breast cancer metastasis." (PMID 39273015, 2024). "Moreover, regulators such as TFAP2C, GTF2I and LMO4 were found to have potential prognostic value for lung metastasis free (LMF) survival of breast cancer." (PMID 31215771, 2019). "However, the knockdown of the other three transcription factors (ELK1, GTF2I and FOXP3) did not reduce UBE2T expression levels in breast cancer cells." (PMID 36338541, 2022).
Primary Sjögren's Syndrome (5 papers, 2021 to 2025). "TFII-I associated polymorphisms are implicated in Sjögren’s syndrome and Lupus in humans and, germline deletion of the Gtf2i gene in mice leads to embryonic lethality." (PMID 36756127, 2023). "Our previous GWAS showed that GTF2I was the most strongly associated gene in Chinese Han patients with primary Sjögren’s syndrome (pSS)." (PMID 34248934, 2021).
acute promyelocytic leukemia (4 papers, 2017 to 2021). An aggressive form of acute myeloid leukemia (AML), characterized by arrest of leukocyte differentiation at the promyelocyte stage, due to a specific chromosomal translocation t(15;17) in myeloid cells. "Mutations of GTF2I and gene fusions have been observed, respectively, in TETs and soft tissue angiofibromas (GTF2I/NCOA2 fusion), acute promyelocytic leukemias (GTF2I/RARA fusion), and pilocytic astrocytoma (GTF2I/BRAF fusion)." (PMID 33915954, 2021). "Occurrence of additional GTF2I-fusions; GTF2I-BRAF 4–10 (primary melanoma), GTF2I-NCOA2 (soft tissue angiofibroma development) and GTF2I-RARA (acute promyelocytic leukemia), further supports a oncogenic role." (PMID 28448514, 2017).
Intellectual disability (4 papers, 2013 to 2024). "Thus, several authors have suggested that GTF2I hemizygosity could be a major cause of intellectual disability in patients with WBS." (PMID 23972161, 2013). "WS is characterised by craniofacial dysmorphology, intellectual disability and hyper-sociability and specifically GTF2I deletion explains many of the social and cognitive features of WS." (PMID 39136782, 2024). "This may be because the genes GTF2I and GTF2IRD1 mainly affect the neurodevelopment related to these two functional regions, but they are not sufficient to cause the intellectual disability symptoms typical for WBS patients." (PMID 35379245, 2022).
myasthenia gravis (4 papers, 2021 to 2023). Myasthenia gravis (MG) is a rare, clinically heterogeneous, autoimmune disorder of the neuromuscular junction characterized by fatigable weakness of voluntary muscles. "In 25 German cases with known myasthenia gravis status, the GTF2I mutation was evident in 11/12 patients with myasthenia gravis (91,7%) and 10/13 myasthenia-free patients (76,9%)." (PMID 34497477, 2021). "GTF2I is the most commonly mutated gene in TETs, and is associated with an increased number of early-stage pathological types, as well as no history of myasthenia gravis or radiotherapy treatment." (PMID 36114454, 2022). "The GTF2I mutation was determined to be related to Masaoka stage I, more indolent pathological subtypes, and no history of myasthenia gravis (MG) or no radiotherapy treatment." (PMID 36114454, 2022).
pilocytic astrocytoma (4 papers, 2017 to 2021). Pilocytic astrocytoma is a rare subtype of low-grade glioma of the central nervous system characterized by a well circumscribed, often cystic, brain tumor with a discrete mural nodule and long, hair-like projections that extend from the neoplastic astrocytes. "It is nevertheless important to note that the presented BRAF multiplexed assay is not designed to detect other rare fusions involving BRAF that have been reported in pilocytic astrocytomas including FAM131:BRAF, RNF130:BRAF, CLCN6:BRAF, MKRN1:BRAF, GNAI1:BRAF, and GTF2I:BRAF." (PMID 33282733, 2020).
thymic epithelial tumors (4 papers, 2022 to 2025). "Even with a dedicated assay for the identification of specific somatic mutations in thymic epithelial tumors, only GTF2I mutations were found to be significantly recurrent." (PMID 37671056, 2023). "General transcription factor IIi (GTF2I) mutations are very common in thymic epithelial tumors (TETs) and are related to a more favorable prognosis in TET patients." (PMID 36114454, 2022). "Finally, a single point mutation in GTF2I is associated with thymic epithelial tumors as well as GTF2I gene fusions are known to occur in various forms of cancers." (PMID 36756127, 2023).